CDK4 (cyclin dependent kinase 4)
Diseases named in the same sentence as CDK4 in open-access papers (continued):
Sharing a sentence is not in itself a finding about the gene and the disease.
breast cancer (continued). "This study aimed to evaluate the efficacy and safety of CDK4/6i in patients with advanced breast cancer (ABC) in a clinical setting." (PMID 37667421, 2023). "Four randomized clinical trials have also investigated the role of adjuvant CDK4/6 inhibitors in addition to endocrine therapy in patients with intermediate and high-risk HR+/HER2− early breast cancer." (PMID 37894292, 2023). "Clinical activity in TNBC and HR+/HER2-breast cancer post-CDK4/6-inhibitor settings warrants further evaluation." (PMID 37488191, 2023). "Here, we study interactions between estrogen receptor-positive breast cancer cell lineages that are sensitive and resistant to ribociclib-induced cyclin-dependent kinase 4 and 6 (CDK4/6) inhibition." (PMID 37386030, 2023). "For instance, ligand-activated AhR inhibits PI3K/AKT signaling pathways accompanied by reduced cyclin D1/D3 and cell division protein kinase 4 (CDK4) in breast cancer cells." (PMID 37241719, 2023). "Dalpiciclib is a CDK4/6 inhibitor, recently approved for treatment in advanced breast cancer patients in China." (PMID 37805496, 2023). "Beyond ER+ breast cancer, promising activity of CDK4/6 inhibitors in mantle cell lymphoma (MCL), liposarcoma, melanoma, non-small cell lung cancer (NSCLC), glioblastoma, neuroblastoma and malignant rhabdoid tumors has been shown." (PMID 36817127, 2023). "CDK4/6 inhibitors combined with endocrine therapy are the standard of care for the treatment of patients with HR+/HER2− advanced breast cancer." (PMID 37894292, 2023). "Our findings suggest a new direction for investigations into resistance, and should be informative for patients with breast cancer treated with CDK4/6 inhibitors." (PMID 36825764, 2023). "We found using datasets associated with resistance to CDK4/6 inhibitors in the Gene Expression Omnibus (GEO) that more CPVL was expressed in resistant, than sensitive breast cancer cells, implying a potential role in regulating drug resistance." (PMID 36825764, 2023). "Cyclin-dependent kinase 4/6 inhibitors (CDK4/6i) play a crucial role in cancer treatment, particularly in breast cancer, and their mechanism of drug resistance is a topic of global interest in research." (PMID 37475713, 2023). "Although CDK4/6i have been shown to be highly effective in treating HR + /HER2- breast cancers, acquired resistance frequently occurs after a period of treatment." (PMID 38037159, 2023). "All three CDK4/6 inhibitors are administered orally, with palbociclib being the first to demonstrate clinical efficacy and extensively investigated in breast cancer treatment." (PMID 37686364, 2023). "CDK4/6 inhibitors are now the mainstay treatment of HR+/HER-2-negative advanced breast cancer in addition to endocrine therapy." (PMID 38162489, 2023). "CDK4/6 and aromatase are validated targets for the treatment of breast cancer, which is currently one of the most frequently diagnosed cancers." (PMID 36985460, 2023). "A significant question for breast cancer clinicians is how the current data landscape for CDK4/6i impacts contemporary patient care." (PMID 36949066, 2023). "The use of cyclin-dependent kinase 4/6 (CDK4/6) inhibitors has changed the clinical treatment paradigm for HR+/HER2− breast cancer." (PMID 37444496, 2023). "A recent study found the upregulation of MDR proteins in CDK4/6 inhibitor-resistant breast cancer cells." (PMID 37511548, 2023). "Although the use of hormone inhibitors, such as tamoxifen, fulvestrant, and aromatase inhibitors, has remained the mainstay of ER + breast cancer treatment, the emergence of resistance has led to the addition of CDK4/6 inhibitors to this therapy." (PMID 36792625, 2023). "The cell cycle checkpoint module is of particular interest, because CDK4/6 inhibitors (CDK4/6i) are currently being used to treat ER+ breast cancer, but there is a dearth of reliable biomarkers for the efficacy of this treatment." (PMID 37394063, 2023).
breast cancer (continued). "The simultaneous inhibition of CDK4/6 and aromatase has established a suitable strategy for treating ER+ breast cancer." (PMID 37682937, 2023). "Currently, three CDK4/6 inhibitors are FDA approved for treatment of metastatic HR+/HER2− breast cancer." (PMID 37704753, 2023). "The combination of T-DM1 and CDK4/6 inhibitors can delay disease progression due to resistance in HER2-positive breast cancer." (PMID 38352694, 2023). "The CDK4/6 complex is an important mediator for transition into S phase and plays an important role in carcinogenesis and the progression of breast cancer." (PMID 37759706, 2023). "The first CDK4/6i to be tested in human breast cancer cell lines was palbociclib (Ibrance®, PD-0332991, Pfizer, New York, NY, USA)." (PMID 36980649, 2023). "To date, the CDK inhibitors (CDKIs), specifically the ones that block the enzyme activity of CDK12/13 and CDK4/6, have been validated as a promising therapeutic treatment in breast cancer." (PMID 36495130, 2023). "Inhibiting PTEN activity in breast cancer resulted in CPVL promoting resistance to CDK4/6 inhibitors, and CPVL knockdown decreased the tumorigenicity of CDK4/6 inhibitor‐resistant cells in mice." (PMID 36825764, 2023). "In breast cancer, the combination of CDK4/6i with endocrine therapy became standard procedure and is certainly essential to restrict adaptive events, via reduction of Cyclin D1 levels and Cyclin E1 activity." (PMID 37964967, 2023). "In this study, we performed an unbiased quantitative high-throughput combinatorial screening (qHTCS) to identify compounds capable of overcoming resistance to CDK4/6i in breast cancer cells." (PMID 37886470, 2023). "Here, we present real-world data (RWD) on CDK4/6i treatment in patients with HR+/HER2− ABC at four certified German university breast cancer centers." (PMID 36876172, 2023). "Abemaciclib was recently licensed by the FDA as the first and only CDK4/6 inhibitor for use in HR+/HER2 node-positive early breast cancer patients with a Ki-67 score of less than 20% and a high risk of recurrence." (PMID 37759823, 2023). "Module 2A explored the safety, tolerability and preliminary efficacy of 2 dose levels of samuraciclib (240 mg OD and 360 mg OD) in combination with fulvestrant in HR+/HER2− advanced breast cancer patients who had previously received CDK4/6 inhibitor therapy." (PMID 37488191, 2023). "Based on these results, the NCCN guidelines recommended SG for the treatment of patients with HR‐positive breast cancer who have received endocrine therapy, CDK4/6 inhibitors and at least two lines of chemotherapy." (PMID 38090370, 2023). "For patients with HR+/HER2 metastatic and high-risk early breast cancer (EBC), there are a number of problems that need to be addressed with the growing clinical usage of CDK4/6 inhibitors." (PMID 37759823, 2023). "One study suggests that breast cancer cells with FGFR1 alterations that exhibit resistance to CDK4/6 inhibitors and fulvestrant can be overcome by combining the FGFR tyrosine kinase inhibitor (TKI) with CDK4/6 inhibitors and ER antagonists." (PMID 37511548, 2023). "Overall, we report a decreased incidence of AI-induced arthralgia in postmenopausal breast cancer patients treated with AI and CDK4/6 inhibitor combination in the adjuvant setting." (PMID 37293258, 2023). "Cyclin-dependent kinase 4/6 inhibitors (CDK4/6i) combined with endocrine therapy are the standard of care for HR-positive/HER2-negative advanced breast cancer patients." (PMID 36902831, 2023). "In conclusion, we found that stromal senescence induced after palbociclib treatment increased metastatic seeding and growth of CDK4/6-inhibitor-resistant breast cancer cells." (PMID 36980794, 2023). "In conclusion, our data suggested a pivotal role for Pak1 in resistance to ET and CDK4/6i in ER+ breast cancers." (PMID 37258566, 2023).
breast cancer (continued). "CDK4/6 inhibitors (CDK4/6i) have emerged as first-line therapeutic strategies for metastatic hormone receptor-positive (HR+) breast cancer and demonstrate promising potential in other malignancies such as non-small-cell lung cancer and melanoma." (PMID 38030655, 2023). "CDK4/6 inhibitors are approved for use in ER+ breast cancers where they significantly increase progression free survival but also suffer from therapy acquired resistance." (PMID 37264081, 2023). "In a relevant biological problem of CDK4/6-inhibitors and breast cancer, the method reproduced known information and revealed novel insights, highlighting that it can be successfully applied in studies involving low-abundance proteins and limited samples." (PMID 37577163, 2023). "Palbociclib has recently been approved for the treatment of advanced breast cancer, targeting CDK4 and CDK630." (PMID 37949959, 2023). "We studied the combined effect of pyrotinib (anti-HER2 drug), tamoxifen (endocrine therapy), and dalpiciclib (CDK4/6 inhibitor) on the HER2+/HR+ breast cancer cell line BT474 to simulate the clinical therapy in MUKDEN 01 trial." (PMID 36602226, 2023). "Taken together, our study suggests that all available CDK4/6i remain viable options in ER+/HER2− advanced breast cancers." (PMID 37958338, 2023). "The addition of CDK4/6 inhibitors to endocrine therapy in advanced hormone receptor-positive HER2-negative breast cancer has led to practice-changing improvements in overall survival." (PMID 36765648, 2023). "The monarcHER trial results prompted a preliminary investigation of MAF1 regulation by the CDK4/6 inhibitor abemaciclib in HER2-positive breast cancer." (PMID 37801436, 2023). "The AVATAR trial recently opened to accrual in Australia, examining SBRT for patients with breast cancer, whose disease progressed on first-line CDK4/6 inhibitors." (PMID 37504365, 2023). "In this study, we generated two ER+/HER2- breast cancer cells resistant to the combination of fulvestrant (ER down regulator) and abemaciclib (CDK4/6i)." (PMID 37258566, 2023). "We fervently expect that CDK4/6 inhibitors will expand their application to additional cancer types in addition to HR+/HER2− breast cancer." (PMID 37759823, 2023). "An observational study was performed to analyze the efficacy, in terms of humoral response and CD4+ and CD8+ cell responses, of COVID vaccination in patients with breast cancer under treatment with CDK4/6i, in comparison to healthy controls." (PMID 37046661, 2023). "In summary, CDK4/6 inhibitors combined with NSAI have shown great efficacy in the treatment of advanced breast cancer." (PMID 37444496, 2023). "A total of 19 patients (22.62%) with advanced breast cancer who received CDK4/6 inhibitors (n=84, ribociclib=47, palbociclib=32, abemaciclib=5) and 3 patients (18.75%) who received an mTOR inhibitor (n=16) were reported to have a PIK3CA mutation." (PMID 37655108, 2023). "Ongoing studies evaluating the use of neoadjuvant endocrine therapy with CDK4/6 inhibitors will offer further insight into optimal neoadjuvant treatment strategies in HR + breast cancer." (PMID 36897465, 2023). "Collectively, our studies shed light on a novel mechanism regulating palbociclib-resistance, and present clinical evidence for developing therapeutic approaches to treat CDK4/6i-resistant breast cancer patients." (PMID 37886470, 2023). "Recently, CDK4/6 inhibitors have gained approval for investigational treatment of breast cancer and various other tumors." (PMID 37686364, 2023). "Breast cancer has been broadly treated with CDK4/6 inhibitors for decades, and this has helped thousands of patients." (PMID 36825764, 2023). "Heckler and colleagues investigated the impact of CDK4/6 inhibitors on activated CD8+ T cells of breast cancer patients and observed that CDK4/6 inhibition resulted in an increased frequency of memory CD8+ T cell precursors." (PMID 36817127, 2023).
breast cancer (continued). "To test the potential of RMC-6272 in CDK4/6 inhibitor resistant breast cancers, we developed palbociclib-resistant (PalboR) MCF-7, ZR-75-1, and T47D breast cancer cell lines through chronic treatment." (PMID 37264081, 2023). "Clinical trials studying the application of CDK4/6 inhibitors in ER+/HER2+ or HR+/HER2+breast cancer." (PMID 38293701, 2023). "Of note, this trial recruited patients prior to the approval of CDK4/6 inhibitors in this breast cancer setting." (PMID 37308971, 2023). "Cell viability, colony formation, cell cycle, and apoptosis assays were used to evaluate the effect of carboxypeptidase vitellogenic like (CPVL) on breast cancer cells under the condition of CDK4/6 inhibitors." (PMID 36825764, 2023). "We investigated factors associated with breast cancer resistance to CDK4/6 inhibitors by downloading the GSE98987, GSE117742, and GSE117743 datasets associated with breast cancer treatment by CDK4/6 inhibitors from the GEO database." (PMID 36825764, 2023). "The CDK4/6 inhibitors significantly increase progression-free survival (PFS) in ER+/HER2− advanced breast cancer patients." (PMID 37958338, 2023). "Although HR-positive breast cancer is considered less immunogenic, CDK4/6 inhibitors magnify immune recognition and the reaction of host immune cells toward tumor cells." (PMID 36635767, 2023). "CDK4/6 inhibitors (CDK4/6i) have been established as standard treatment against advanced Estrogen Receptor-positive breast cancers." (PMID 37964967, 2023). "The three CDK4/6 inhibiting agents showed more favorable outcomes when combined with the mainstay hormonal therapy for HR+/HER-2 breast cancer patients in terms of prolonged survival compared to their comparator endocrine therapy alone." (PMID 38162489, 2023). "FDA-approved CDK4/6 antagonists for the treatment of various types of breast cancer include palbociclib, abemaciclib, and ribociclib." (PMID 37415164, 2023). "Here, we reported that PARP1 was amplified in breast cancer cells and CDK4/6i-resistant patients, and knockdown or inhibition of PARP1 reversed drug resistance in cell experiments and animal models." (PMID 38037159, 2023). "CDK4/6i combined with endocrine therapy is the standard of care for patients with HR + /HER2- advanced breast cancer." (PMID 38037159, 2023). "Carboxypeptidase vitellogenic like negatively regulates phosphatase and tensin homolog to impact the anticancer effects of cyclin‐dependent kinase 4 and 6 inhibitors in breast cancer." (PMID 36825764, 2023). "This study aimed to determine the vaccination response in a specific subgroup of breast cancer patients receiving treatment with CDK4/6 inhibitors." (PMID 37046661, 2023). "Our findings of viability curves and colony formation showed that CPVL promoted breast cancer cell resistance to CDK4/6 inhibitors." (PMID 36825764, 2023). "Unfortunately, there is currently no consensus regarding standard of care for the treatment of women with advanced HR+/HER2− breast cancer whose disease progresses on CDK4/6 inhibition." (PMID 37488191, 2023). "We demonstrate a new mechanism underlying anti-HER2 resistance and provide the rationale for using a combination of anti-HER2 and CDK4/6 inhibitors in HER2-positive breast cancer." (PMID 37160904, 2023). "ER + breast cancer cells transduced with Fibroblast growth factor receptor 1 (FGFR1) was resistant to CDK4/6i." (PMID 37475713, 2023). "The HER2 kinase inhibitors lapatinib and tucatinib, as well as the CDK4/6 inhibitors ribociclib and palbociclib, have all been given the green light for the treatment of breast cancer." (PMID 37711177, 2023). "Although abemaciclib has shown efficacy in HR + /HER2- breast cancer patients, many patients demonstrate intrinsic or acquired resistance to CDK4/6i and disease progression." (PMID 38037159, 2023).
breast cancer (continued). "The target drugs for breast cancer were located in the CMGC group as inhibitors of CDK4/6, which are involved in the cell cycle control pathway and are checkpoints of G1/S phase." (PMID 37064116, 2023). "Cyclin-dependent kinase 4/6 (CDK4/6) is one kinase that is frequently overactivated in breast cancer, leading to cell cycle progression by phosphorylating retinoblastoma (Rb) protein." (PMID 37711177, 2023). "We next investigated if BCSC-secreted IL8 modulates the sensitivity of CDK4/6 inhibitor in ER + breast cancer cells." (PMID 36915147, 2023). "An observational prospective study was performed on 35 women with breast cancer with an active CDK4/6i treatment in combination with endocrine therapy, who were scheduled to receive the mRNA-1273 SARS-CoV-2 vaccine." (PMID 37046661, 2023). "Palbociclib, an orally bioavailable CDK4/6i, has been proved to induce cell-cycle arrest in endocrine-resistant breast cancer cell lines and to have synergistic anti-tumor effects in preclinical studies." (PMID 36717797, 2023). "As ER signaling was potentiated by the BCSC secretome, it was further investigated if the BCSC secretome modulates the expression of CYCLIN D1 as well as the sensitivity to CDK4/6 inhibitor in breast cancer." (PMID 36915147, 2023). "The use of CDK4/6 inhibitors has been the first-line treatment paradigm for HR+/HER2− breast cancer." (PMID 37444496, 2023). "The phase II PACE trial similarly enrolled patients with advanced ER+/HER2-breast cancer who received prior AI and CDK4/6 inhibitor, of which 91% received palbociclib." (PMID 37035239, 2023). "TMTV and metabolic response by Deauville score were significant prognostic factors for PFS in patients with breast cancer treated with CDK4/6i." (PMID 37519806, 2023). "Previous studies demonstrated that CDK4/6i can increase the immunogenicity and response to ICIs in models of breast cancer and other cancer types by influencing the tumor cells and TME through several mechanisms." (PMID 37450351, 2023). "Cyclin-dependent kinase 4/6 inhibitors (CDK4/6i) in combination with endocrine therapy are the standard of care approach in the first- or second-line setting for HR+/HER2− advanced breast cancer." (PMID 36902831, 2023). "This assessment can provide a reference basis for Chinese medical institutions to select CDK4/6 inhibitors for treating HR+/HER2− advanced breast cancer and optimize the drug catalog." (PMID 37800838, 2023). "In postmenopausal women receiving AI as initial therapy for ER+ mBC, adding a CDK4/6 inhibitor improved PFS in 3 randomized phase III trials (PALOMA [PALbociclib: Ongoing trials in the MAnagement of breast cancer]-2, MONARCH 3, MONALEESA-2)." (PMID 37369022, 2023). "For example, the combination of CDK4/6 inhibitors with PI3K/AKT/mTOR pathway inhibitors such as alpelisib in breast cancer cell lines and patient-derived models has demonstrated that alpelisib can overcome resistance mediated by PI3K pathway activation." (PMID 37511548, 2023). "Given CDK4/6’s potent activity in breast cancer cells, researchers aimed to inhibit this activity in conjunction with AR inhibitors." (PMID 38067367, 2023). "This was due to the approval of several new drugs effective for endocrine resistant breast cancer (mTOR and CDK4/6 inhibitors) emerging during the conduct of this study." (PMID 36441436, 2023). "In our systematic review of phase III RCTs, arthralgias were reported in 13.2 to 68.7% of patients receiving AIs for early-stage breast cancer, while arthralgias induced by CDK4/6 inhibitors occurred in a much lower rate [20.5–41.2%]." (PMID 37293258, 2023). "Here, the authors use experimental and mathematical models to explore interactions between ER+ breast cancer cell lineages that are sensitive or resistant to CDK4/6 inhibition, revealing the role of facilitative growth." (PMID 37386030, 2023).